TPTE2 (transmembrane phosphoinositide 3-phosphatase and tensin homolog 2)
Description:
Acts as a lipid phosphatase, removing the phosphate in the D3 position of the inositol ring from phosphatidylinositol 3,4,5-trisphosphate. [Isoform 4]: Shows no phosphoinositide phosphatase activity.
Synonyms: TPIP
Tractability: Antibody: UniProt predicts a signal peptide or a membrane-spanning region.
Gene: Protein-coding gene on chromosome 13 (19,422,876 to 19,561,625, reverse strand). Ensembl gene ENSG00000132958.
Subcellular location: Endoplasmic reticulum membrane (Isoform 3); Endoplasmic reticulum membrane (Isoform 1); Golgi apparatus membrane; Cytoplasm (Isoform 4)
Subcellular location (Human Protein Atlas): Cytosol; Endoplasmic reticulum
Pathways (Reactome):
Metabolism: Synthesis of PIPs at the Golgi membrane
Gene Ontology:
Molecular function: phosphatidylinositol-3,4,5-trisphosphate 3-phosphatase activity; phosphatidylinositol-3,4-bisphosphate 3-phosphatase activity; monoatomic ion channel activity; phosphatase activity
Biological process: phosphatidylinositol biosynthetic process; monoatomic ion transmembrane transport; monoatomic ion transport; transmembrane transport
Cellular component: cytoplasm; endoplasmic reticulum; endoplasmic reticulum membrane; Golgi membrane; cytosol; membrane
Genetic constraint (gnomAD): Loss-of-function variants: 43 observed, 57.75 expected, observed/expected ratio (o/e) 0.74, 90% interval 0.58 to 0.96. The upper end of that interval is the gene's LOEUF score, 0.96, which puts it in group 4 of 6, group 1 being the genes least tolerant of losing a copy. Missense variants: 393 observed, 494.94 expected, observed/expected ratio (o/e) 0.79, 90% interval 0.73 to 0.86. Synonymous variants: 141 observed, 168.73 expected, observed/expected ratio (o/e) 0.84, 90% interval 0.73 to 0.96.
Homologues: Orthologues: chimpanzee TPTE2 (93% identical), mouse Tpte (64% identical), rat Tpte2 (64% identical), tropical clawed frog tpte2 (51% identical), zebrafish tpte (50% identical). Paralogues in human: TPTE (88% identical), PTEN (24% identical), TNS1 (20% identical), TNS3 (17% identical), TMEM266 (8% identical), HVCN1 (6% identical).
Diseases named in the same sentence as TPTE2 in open-access papers:
TPTE2 is named in the same sentence as 9 diseases in open-access papers, as found by Europe PMC text mining. Sharing a sentence is not in itself a finding about the gene and the disease. The quoted sentences say what the papers report.
breast carcinoma (1 paper, 2025). "Our database identified well-known fusion genes that are commonly associated with breast cancer, such as ESR1::CCDC170, and revealed previously unreported fusion genes, including TPTE2::MRPS31P2 and LHFPL5::CLPSL1." (PMID 41213951, 2025). "The most frequently occurring fusion genes in each subtype were TTC6::MIPOL1 in HR+/HER2‒ breast cancers, LHFPL5::CLPSL1 in triple-negative breast cancer (TNBC), and TPTE2::MRPS31P2 in HER2+ breast cancers." (PMID 41213951, 2025).
liver fibrosis (1 paper, 2022). "Further, TPTE2 has been shown to be related to hepatic fibrogenesis and fibrosis; alchohol abuse is one of the main causes of liver fibrosis." (PMID 36371147, 2022).
male infertility (1 paper, 2021). The inability of the male to effect fertilization of an ovum after a specified period of unprotected intercourse. "Based on these data, while we predict mutations in TPTE2 are likely to result in male infertility, a specific link to the mechanisms underpinning sperm tail assembly is lacking." (PMID 34089056, 2021).
melanoma (1 paper, 2023). A malignant, usually aggressive tumor composed of atypical, neoplastic melanocytes. "Further, RT‐PCR revealed that TPTE2 is expressed in two‐thirds of the melanoma cell lines tested." (PMID 36219477, 2023).
tumor (1 paper, 2013). "The literature on TPTE2 is limited and it indicates that TPTE2 can inhibit cell growth and initiate apoptosis, similar to the PTEN tumor suppressor." (PMID 23826350, 2013).
TPTE2 also shares sentences with these, for which no sentence is quoted: breast tumors (1 paper); cancer (1); Epileptic encephalopathy (1); triple-negative breast carcinoma (1).